INS (insulin)
Diseases named in the same sentence as INS in open-access papers (continued):
Sharing a sentence is not in itself a finding about the gene and the disease.
diabetes (continued). "In categorical variables, diabetes mellitus, cerebral infarction, peripheral artery disease, insulin use, ACE inhibitor use, and diuretics use were associated with elevated log-NLR." (PMID 31014150, 2019). "The impact of higher carbohydrate consumption in this population on lipid and diabetes associated risk factors is consistent with the view that the features of MetS relate to defective insulin action including inflammation and altered fatty acid partitioning." (PMID 31541144, 2019). "The main type of treatment for diabetes and controlling the associated hyperglycemia is in the form of insulin that primarily focuses on lowering and maintaining blood glucose levels." (PMID 31137754, 2019). "The destruction of pancreatic β cells leads to reduced insulin secretion and eventually causes diabetes." (PMID 31822470, 2019). "Diabetes Mellitus (DM, diabetes) is a group of metabolic diseases characterized by the occurrence of persistent hyperglycemia due to deficiency in insulin secretion, insulin action or both." (PMID 31574113, 2019). "Diabetes, associated with insulin resistance and reduction in the level of insulin, mainly affects psychomotor activity, attention, learning, memory, cognition, mental flexibility in the brain." (PMID 31068802, 2019). "Of the selected preoperative factors potentially influencing diabetes remission, longer duration of diabetes, higher baseline HbA1c, high age, and insulin treatment were all associated with lower remission rates 2 years after surgery." (PMID 31747392, 2019). "Recurrent catecholamine production due to recurrent hypoxemia in OSA can impair glucose tolerance, reduce insulin sensitivity and cause type 2 diabetes mellitus." (PMID 31330779, 2019). "Reduction of central obesity is accompanied by normalization of insulin secretion and hepatic insulin sensitivity, thereby reversing the underlying biochemistry of pre-diabetes." (PMID 31242690, 2019). "Abnormally hypertrophic adipocytes induce inflammation, which is closely associated with adipose tissue dysfunction and impaired insulin sensitivity in obesity-mediated diabetes." (PMID 31878002, 2019). "Total pancreatectomy (TP) leads to pancreatic exocrine deficiency and poorly controlled diabetes despite insulin treatment." (PMID 29159772, 2019). "Diabetes mellitus (DM) is a group of endocrine and metabolic disorders with booming prevalence worldwide, caused by insufficient insulin secretion or decreased sensitivity to insulin in peripheral tissues." (PMID 30717466, 2019). "Diabetes mellitus is a multifactorial metabolic syndrome characterized by defect in the secretion of insulin associated with deregulation in carbohydrate, protein, and lipid metabolism." (PMID 31186667, 2019). "We aimed to determine the prevalence and characteristics of type 1 diabetes defined by severe endogenous insulin deficiency in patients >30 years of age with insulin-treated diabetes." (PMID 30969375, 2019). "Diabetes mellitus (DM) is caused by a defect in insulin secretion and/or insulin resistance leading to persistent hyperglycemia, affecting millions of people worldwide." (PMID 30931324, 2019). "Vitamin D has been proposed to have a relevant role into glucose and insulin homeostasis and, if low, as a risk factor for diabetes onset and progression." (PMID 31200589, 2019). "Insulin use is an independent risk factor of DR progression in US adults with diabetes (OR, 3.23; 95% CI, 1.99–5.26)." (PMID 31331327, 2019). "Diabetes is generally caused by the impairment or insufficient β-cells in the pancreas that diminishes insulin biosynthesis and gradually deteriorates whole body functions." (PMID 31337059, 2019). "Failure of the pancreas to produce enough insulin and the body’s inefficient use insulin are both pathologic causes of diabetes." (PMID 31557898, 2019). "Overmuch cholesterol in the cell will impairs insulin secretion in the pancreas, and possibly increases the risk of diabetes." (PMID 31010439, 2019).
diabetes (continued). "The common causes of DKA are missed dose of insulin, illness or infection, and undiagnosed or untreated diabetes." (PMID 30871605, 2019). "Few studies have examined the associations between the faecal microbiome and insulin sensitivity and secretion using gold-standard methods in high-risk populations prior to diabetes onset." (PMID 30987356, 2019). "ROS can damage β cells by oxidative stress, lead to a decreased number of β cells and insulin secretion in the pancreas, and later induce insulin resistance, eventually causing or aggravating diabetes." (PMID 30941199, 2019). "This study is the first nationally representative study reporting patterns of insulin therapy, especially using pen devices and the associated health outcomes in an adult population with diabetes in Iran." (PMID 31461470, 2019). "The diabetes-prone KK strain of mice subjected to ozone (0.5 ppm, 5 h/day for 13 weekdays) had a further impaired insulin response linked to reduced plasma insulin and leptin levels." (PMID 31354743, 2019). "Previous CVD conferred a risk similar to having diabetes in patients who required glucose-lowering medication, used insulin or had albuminuria, or if they had a longer duration of diabetes, i.e., 10–15 years." (PMID 31216703, 2019). "This approach, which is coherent with the recommendations recently issued by the American Diabetes Association, is based on interventions that are insulin sensitizing, to limit the CV risk associated with excessive insulin dosing, and nephroprotective." (PMID 31212638, 2019). "The specific complement of cellular redox machinery required for normal insulin output or to maintenance of insulin secretion under conditions of nutrient excess, obesity, or genetic predisposition to diabetes is undefined." (PMID 31184304, 2019). "In the current review, we summarized the role of Cdc42 in insulin secretion, as well as the relationship between Cdc42 and diabetes-associated diseases, including IR, DN, and cancer." (PMID 30621321, 2019). "Intrauterine environment in moderate diabetes is associated with deficiencies in insulin secretion in adult life, while pups born from mothers with severe diabetes present depleted insulin action in adult life." (PMID 31717560, 2019). "Two major forms of diabetes are recognised: type 1 (T1D) has a young age of onset and results in loss of insulin-secreting β cells and a lifetime requirement for insulin replacement therapy." (PMID 30635569, 2019). "In monogenic diabetes, insulin secretion is deficient entirely based on mutations in genes that are important for beta cell function." (PMID 31161346, 2019). "Several studies have identified that adverse events were related to the severity of diabetes; for example, glycosylated hemoglobin (HbA1c) level and insulin therapy were independent risk factors for the development of post-surgery complications." (PMID 31890044, 2019). "Modern diabetes management modalities, including glucagons like peptide-1 receptor agonist-based therapy, novel types of insulin, modern insulin pumps, and bariatric surgery, are associated with a significant reduction of GV." (PMID 31886089, 2019). "In a retrospective cross-sectional study, Yan and Ma found that fasting serum glucose concentration, HbA1c level, diabetes duration, and insulin treatment are potential risk factors for DR in northern Chinese patients with T2DM." (PMID 31045779, 2019). "Islet transplantation (ICTx) is one of the therapeutic options for patients with type 1 diabetes mellitus and can remove the need for insulin injections and associated complications." (PMID 31341242, 2019). "The phenotype of Manf−/− mice is characterized by the progressive loss of circulating insulin leading to diabetes and a severe growth defect." (PMID 31781038, 2019). "Diabetes is a chronic disease characterized by an insulin deficiency and/or insulin insensitivity, and was the seventh leading cause of death in 2016." (PMID 31703341, 2019).
diabetes (continued). "Metabolic syndrome is a medical condition that predisposes individuals to diabetes and atherosclerotic cardiovascular disease (National Institutes of Health, 2002) whereas insulin resistance leads to a progressive development of diabetes." (PMID 31178745, 2019). "The American Diabetes Association recommends that patients with severe disease have blood glucose levels > 180 mg/dL and need to start insulin treatment, and the recommended target glucose range is from 140 to 180 mg/dL." (PMID 31272376, 2019). "Most of the GB health benefits studied were related to the gastrointestinal symptoms/diseases, followed by the glycemic/insulin metabolism, weight control, and renal and liver complications associated to diabetes." (PMID 31146437, 2019). "For example, in an “artificial pancreas” model, a continuous glucose sensor linked to an insulin pump can automatically dose insulin in patients with diabetes." (PMID 30868107, 2019). "It was also reported that glutamine is associated with insulin sensitivity and reduced diabetes risk." (PMID 31697702, 2019). "Insufficient insulin leads to the accumulation of lipids, specifically TG and TC, in hyperglycemic patients, and thus causes diabetes-related complications." (PMID 31134090, 2019). "Diabetes is an endocrine disorder that is associated with dysregulation of carbohydrate metabolism and deficiency of insulin secretion or insulin action, causing chronic hyperglycemia." (PMID 31344785, 2019). "This is consistent with prior studies that show that age induces a decrease of insulin sensitivity and/or insulin resistance and that age is associated with a higher odds of diabetes prevalence, using regression-based methods." (PMID 31469876, 2019). "An accurate treatment including a mixture of lifestyle indicators and sufficient insulin is required for these patients in order to boost their glycemic control and inhibit diabetes-associated complications." (PMID 31685799, 2019). "In particular dietary fibre is reported to regulate insulin which helps reduce diabetes risk and green leafy vegetables are inversely related to diabetes." (PMID 30699173, 2019). "Type 2 diabetes mellitus starts off with a reduced action of insulin, which subsequently leads to a deficient insulin secretion and reduction of β-cell mass as well." (PMID 31387633, 2019). "Diabetes mellitus is a chronic disease caused by inherited or acquired deficiency in insulin secretion and by decreased responsiveness of the organs to secreted insulin." (PMID 31037617, 2019). "Most patients with KCNJ11 and ABCC8 mutations have isolated diabetes, and their treatment can be switched from subcutaneous insulin injections to treatment with oral sulfonylureas (SU)." (PMID 31441606, 2019). "Diabetes can be classified into two types based on their controlled mechanism: type 1 caused by inadequate insulin production in the body and type 2 governed by the body’s inability to use its produced insulin." (PMID 30997590, 2019). "While hyperinsulinemia is a main aspect of the metabolic syndrome, conversely decreased insulin levels in diabetics are linked with accelerated aging." (PMID 31031804, 2019). "Regarding the modifying effect of diabetic medication, treatment with insulin was associated with an increased risk of diabetes-related mortality compared to participants treated with oral medication or diet only." (PMID 31774849, 2019). "The main findings from this 5-cohorts pooled analysis of 3,590 individuals with diabetes, is that using insulin was associated with 50% increased dementia risk compared to using other treatments for diabetes." (PMID 30768625, 2019). "In particular, decreased insulin secretion due to reduced pancreatic β cell mass is considered the leading cause of the onset and exacerbation of diabetes." (PMID 31357734, 2019). "Insulin corrects hyperglycemia; however, it is unclear if it reverses other abnormalities caused by diabetes." (PMID 30503832, 2019).
diabetes (continued). "We propose that these markers should be used in combination with adiponectin, leptin, and insulin for the early detection of the risk of diabetes." (PMID 31379415, 2019). "For example, pancreatic β-cell dysfunction leads to insulin secretion resistance which in turn causes hyperglycemia and diabetes." (PMID 31842349, 2019). "Insulin resistance (IR) is a vital hallmark of type 2 diabetes mellitus, which is characterized by an impaired ability of insulin to promote glucose uptake and utilization." (PMID 31019978, 2019). "Initially it was believed that antipsychotics increased the risk of diabetes by promoting weight gain but there is also evidence that antipsychotics directly decrease insulin sensitivity and insulin secretory capacity." (PMID 31478094, 2019). "Being a member of the diabetes association was strongly associated with a favorable attitude and adherence to insulin use." (PMID 31915711, 2019). "Increased level of LDH activity in diabetic rats as compared to normal control rats is linked with less insulin availability in diabetes." (PMID 30944708, 2019). "Gluteofemoral AT, which is measured based on the hip or thigh circumference or thigh AT mass, is inversely associated with serum cholesterol and insulin levels and is independently associated with a lower risk of diabetes mellitus and coronary heart disease." (PMID 31480613, 2019). "Over expression of IGFBP-2 by an adenovirus leading to very high concentrations of IGFBP-2 reversed diabetes in insulin-resistant ob/ob mice, diet-induced obese mice, as well as insulin-deficient streptozotocin-treated mice." (PMID 30392760, 2019). "Diabetes mellitus is a chronic disease characterized by changes in saccharide, lipid and protein metabolism resulting from a deficiency in insulin secretion from the pancreas, insulin resistance or both." (PMID 31091784, 2019). "Diabetes mellitus is a chronic metabolic disorder characterized by hyperglycaemia and insulin secretion impairment caused by β cell dysfunction or death." (PMID 31861156, 2019). "Kazemi et al13 assessed the association between HbA1c trajectory and diabetes‐related clinical factors including general types of treatment (e.g. diet, insulin and non‐insulin medications)." (PMID 30848039, 2019). "Diabetes mellitus (DM) is a chronic metabolic disorder characterized by a relative or absolute deficiency in circulating insulin levels, resulting in high blood sugar levels over a prolonged period 1-3." (PMID 31839754, 2019). "Type 1, or autoimmune, diabetes is caused by the T-cell mediated destruction of the insulin-producing pancreatic beta cells." (PMID 31821343, 2019). "More recently, IL-13, as an inflammatory marker, was found to be associated with the conversion of normoglycemia into type 2 diabetes mellitus and the initiation of insulin therapy." (PMID 31656196, 2019). "There are monogenic forms of diabetes where defining the genetic cause has a dramatic impact on treatment—with patients being able to transition from insulin to sulfonylureas." (PMID 31012484, 2019). "Diabetes, characterized by an elevated blood glucose level due to insufficient insulin production, is a heterogeneous disease with multiple causes." (PMID 31835423, 2019). "STZ is a broad-spectrum antibiotic, which is widely administered to experimental animals to induce diabetes; this antibiotic elicits toxic effects on the pancreatic β cells of pancreatic islets and thus causes the loss of insulin secretion of the islets." (PMID 31209719, 2019). "Diabetes is generally characterized by hyperglycemia resulting in deficiency or insensitivity to endogenous insulin with increased hepatic glucose production." (PMID 30944708, 2019). "For women with pre-existing diabetes who become pregnant, an ACOG Practice Bulletin (#60) in 2005 and a consensus statement by the American Diabetes Association in 2008 recommend insulin as the primary method of glycemic control." (PMID 31775682, 2019).
diabetes (continued). "Lifestyle modification, including exercise and a healthier diet (low-fat diet rich in complex carbohydrates fresh fruits, vegetables) are associated with the reduction in the incidence of Type 2 Diabetes mellitus and improved insulin sensitivity." (PMID 31591373, 2019). "Research suggests that diabetic people who smoke have poorer diabetes control, greater insulin needs, increased insulin resistance and increased risk of hypoglycemia." (PMID 31461485, 2019). "In support of this concept, triggering glucagon signalling deteriorates glycemia in diabetes and obesity, both of which are associated with insulin insensitivity." (PMID 30626440, 2019). "Diabetes can be caused by impaired glucose tolerance and decreased insulin secretion from beta cells of the pancreas, due to the antagonistic effects of olanzapine." (PMID 32133067, 2019). "In this review, we summarized the regulation of Cdc42 in insulin secretion and diabetes-associated diseases." (PMID 30621321, 2019). "Contrastingly, we found that diabetes duration, presence of microvascular complications, being treated with insulin and number of antihypertensives were associated with poorer disease control." (PMID 31729951, 2019). "Close to diabetes onset (0–2 months prior to diagnosis), unmethylated INS ratios were associated with mIAA (p = 0.003), IA-2A (p = 0.014), and ECL-IAA (p = 0.002) levels." (PMID 31398795, 2019). "At least two of them are clearly pathogenic alterations responsible for monogenic diabetes: p.Gly32Ser in the INS gene and p.Val264fs in the HNF1A gene." (PMID 31365591, 2019). "Diabetes mellitus is a pathological state resulting from an absolute or relative deficiency of insulin in the body." (PMID 31200538, 2019). "In the next section, we will discuss the role of MPs in the onset and maintenance of cellular dysfunction and injury associated with insulin resistant states and diabetes with special emphasis on the molecular mechanisms involved." (PMID 30915196, 2019). "Maturity-onset diabetes of the young (MODY) is a heterogenic group of at least 13 single gene diseases characterized by autosomal dominant inheritance, diabetes onset in adolescents or young adults, and insulin deficiency with preserved insulin secretion." (PMID 30778899, 2019). "In female diabetes patients, oral agents and insulin injection significantly caused more depressive symptoms than oral agents alone according to statistics." (PMID 31726788, 2019). "Ins2*Y16A), prevents the development of autoimmune diabetes, supporting the observation that insulin, and the B9–23 epitope in particular, is clearly an important auto-antigen in the modulation of susceptibility to diabetes in mice and humans." (PMID 30899071, 2019). "Meanwhile, comorbidity with diabetes or hypertension and use of metformin or insulin were also risk factors for PLA recurrence." (PMID 31395935, 2019). "These surprising results strongly suggest that insulin and IR are primarily responsible for the increased risk of restenosis in insulin resistance and diabetes." (PMID 31562314, 2019). "Prospective associations between protein levels and diabetes, prediabetes as well as continuous fasting and 2 h glucose, fasting insulin and insulin resistance were investigated using regression models adjusted for established risk factors." (PMID 30599058, 2019). "Type 1 diabetes mellitus is an autoimmune disease characterized by a deficiency of insulin production by the pancreas." (PMID 31299986, 2019). "The systemic gradual impairment of insulin production and signalling in diabetes is associated with increased myocardial FFA uptake whilst mitochondrial FFA uptake and oxidation is reduced." (PMID 31440740, 2019). "Adjusting for a baseline unmethylated INS ratio, an increased rate of change in unmethylated INS ratio from baseline to diabetes onset was associated with a five-year decrease in age at T1D diagnosis (p = 0.04)." (PMID 31398795, 2019).